DES (desmin)
Diseases named in the same sentence as DES in open-access papers (continued):
Sharing a sentence is not in itself a finding about the gene and the disease.
rhabdomyosarcoma (continued). "We analyzed a much larger cohort of 49 primary rhabdomyosarcoma tumor samples of various subtypes, collected over a period of 9 years, for the presence of MYOD1 (L122R), PIK3CA (H1047), and PIK3CA (E542/E545) mutations, along with immunohistochemical analysis of desmin, myogenin, and MYOD1." (PMID 27562493, 2016). "Additionally, pPNET can be differentiated from rhabdomyosarcoma, which is positive for desmin and myogenin, and lymphoma, which may be excluded by immunostaining for LCA and other lymphohematopoietic markers." (PMID 25435942, 2015). "Immunohistochemically sclerosing rhabdomyosarcoma in adults shows a distinctive immunophenotype in the expression of muscle markers, characterized by positivity for MyoD1, negativity for Myogenin and variable expression for Desmin and Actin muscle specific, as occurred in the elbow tumor." (PMID 20701800, 2010). "Virtually all examples of TFCP2-rearranged rhabdomyosarcoma are diffusely positive for pancytokeratins, e.g., AE1/AE3, OSCAR, MNF116, and desmin, as well as myogenin and/or MYOD1, with MYOD1 showing higher sensitivity." (PMID 40526340, 2025). "Desmin is also seldom expressed in PPSS, which helps distinguish it from rhabdomyosarcoma, where it is a common marker." (PMID 40718269, 2025). "In immunohistochemical staining, rhabdomyosarcoma (RMS) exhibits positive expression of vimentin, desmin, myogenin, and MyoD1." (PMID 40703554, 2025). "Positivity for desmin and WT1 nuclear staining in addition to positive epithelial markers strongly favors a diagnosis of DSRCT over that of Ewing sarcoma and rhabdomyosarcoma." (PMID 31103034, 2019). "We observed that the rhabdomyosarcoma cell lines expressed their signature markers MYOD1 as well as downstream myogenic genes MYOGENIN and DESMIN." (PMID 30446688, 2018). "Melanoma, lymphoma and rhabdomyosarcoma can be identified with immunohistochemistry for S100, CD45, and desmin, respectively." (PMID 27413360, 2016). "The tumor cells were positive for Desmin and Myogenin, while only a few cells were positive for ALDH1, suggesting that the ALDH1high cells promoted rhabdomyosarcoma and were reconstituted to incorporate the full heterogeneity." (PMID 25915760, 2015). "The negative staining for cytokeratins, desmin, myogenin, and leukocyte common antigen helps exclude carcinoma, rhabdomyosarcoma, and lymphoid malignancies, respectively." (PMID 40084340, 2025). "Desmin or other muscle-specific markers were not included in the immunohistochemical panel, which represents a limitation in definitively excluding rhabdomyosarcoma or other sarcomas with muscular differentiation." (PMID 41375544, 2025). "However, the discovery of rhabdomyoblast‐like cells with positive skeletal muscle differentiation markers (Desmin, MyoD1, and Myogenin) in the stromal background, raised the possibility of alternative diagnoses, such as PIS‐DICER1 or rhabdomyosarcoma." (PMID 40040389, 2025). "Focal desmin positivity was seen in two of our cases but the lack of nuclear positivity for MyoD1 and myogenin ruled out a rhabdomyosarcoma." (PMID 37218666, 2024). "The malignant cells being negative for Desmin and MyoD1 negated the possibility of rhabdomyosarcoma, and negativity for LCA helped rule out lymphoma." (PMID 39021466, 2024). "Other sarcomas such as rhabdomyosarcoma, gastrointestinal stromal tumor, or mast cell tumor were excluded by negative immunohistochemical reaction with anti-desmin and c-kit antibodies and Giemsa stain negative." (PMID 32349235, 2020). "Rhabdomyosarcoma is often positive for smooth muscle actin, desmin, and myogenin; all of them were negative in our patients." (PMID 22312368, 2012). "Desmin and myogenin immunoreactivity can be used to differentiate rhabdomyosarcoma from other round cell tumors without rhabdomyoblastic differentiation but not sarcomatoid carcinoma with rhabdomyoblastic differentiation." (PMID 21762516, 2011).
rhabdomyosarcoma (continued). "Desmin and PanCK came out negative, ruling out rhabdomyosarcoma and synovial sarcoma, respectively." (PMID 40932977, 2025). "Staining for myoglobin, a marker for rhabdomyosarcoma, was equivocal, and desmin was negative." (PMID 41245941, 2025). "In addition to SMA and desmin, alveolar and embryonic rhabdomyosarcoma express MyoD1 and myogenin but not CK or neuroendocrine markers." (PMID 34193155, 2021). "In those cases of ESFTs which display focal positivity for S100 or desmin, additional immunohistochemical stains for melanoma markers (HMB45, Melan-A) and specific skeletal muscle markers (myogenin, myoD1) can be utilized to exclude melanoma and rhabdomyosarcoma." (PMID 27413360, 2016). "Desmin was similarly negative, helping to exclude the differential diagnosis of rhabdomyosarcoma." (PMID 25254132, 2014). "Rhabdomyosarcoma was excluded by negative staining to myogenin and desmin." (PMID 22540324, 2012). "However, the lack of desmin, myogenin and MyoD-1 ruled out rhabdomyosarcoma, while LCA negativity ruled out a diagnosis of lymphoma." (PMID 20233457, 2010). "Lack of staining with desmin and myoglobin excludes the possibility of rhabdomyosarcoma." (PMID 19700883, 2009). "Bearing this in mind, the only case with focal rhabdoid morphology on a sarcomatoid background which does express desmin (but no SMA) might be interpreted as a heterologous differentiation along the rhabdomyosarcoma line arising in an otherwise unclassified RCC with sarcomatoid component." (PMID 29182526, 2017). "Our differentials were ruled out due to the negative immunohistochemistry of NKX2.2, WT1, S-100, HMB-45, Desmin, and PanCK that ruled out Ewing sarcoma, CIC-DUX4 sarcoma, clear cell sarcoma of soft tissue, rhabdomyosarcoma, and synovial sarcoma, respectively." (PMID 40932977, 2025). "Whereas lymphoma, rhabdomyosarcoma, small cell carcinoma, desmoplastic small round cell tumor and neuroblastoma were excluded by negative staining for cytokeratin, CD20, CD3, desmin, myogenin, synaptophysin and chromogranin A." (PMID 40950824, 2025). "Additionally, negative staining for NKX2.2, CD99, desmin, S100, SOX10, HMB45, GATA3, CD45 (LCA), CD3, and CD20 further excluded diagnoses of Ewing sarcoma, rhabdomyosarcoma, melanoma, and the majority of non-Hodgkin lymphomas." (PMID 39404971, 2024). "The tumor cells were positive for CD68, S100, CD4 and lymphocyte common antigen, while epithelial membrane antigen, HMB-45, CK AE1/AE3, myogenin, desmin, CD1a, CD21 and SALL-4 were negative thus ruling out rhabdomyosarcoma, extrarenal rhabdoid tumor, Langerhans cell sarcoma and malignant melanoma." (PMID 31890359, 2019).
leiomyoma (91 papers, 2006 to 2026). A well-circumscribed benign smooth muscle neoplasm characterized by the presence of spindle cells with cigar-shaped nuclei, interlacing fascicles, and a whorled pattern. "Leiomyoma can also arise in association with muscularis mucosae and present as a polypoid lesion but display a smooth muscle cell immunophenotype that is strongly and diffusely positive for desmin and actin." (PMID 21663626, 2011). "Histopathological examination revealed a leiomyoma with prominent angioleiomyomatous features, characterized by spindle cells surrounding thick-walled vascular structures and immunopositivity for desmin, smooth muscle actin, and progesterone receptor." (PMID 40978684, 2025). "Tumor cells were diffusely positive for anti-smooth muscle antibodies, HHF35, and Desmin, and leiomyoma was suspected." (PMID 40322727, 2025). "For example, inflammatory myofibroblastic tumors are always positive for SMA and ALK-1, leiomyomas are always positive for Desmin and Caldesmon, GIST is positive for CD117, CD34, and DOG-1, schwannomas are positive for S100, etc.." (PMID 39188678, 2024). "For example, c-kit (CD117) or DOG1 is present in GISTs; desmin in leiomyomas; S-100 in schwannomas; smooth muscle actin in glomus tumors; anaplastic lymphoma kinase in inflammatory myofibroblastic tumors; and chromogranin A and synaptophysin in carcinoids." (PMID 38983989, 2024). "On immunohistochemical evaluation, leiomyomas show positive staining for vimentin, smooth muscle actin, and desmin." (PMID 39280874, 2024). "Immunohistochemical markers, specifically smooth muscle antigens like specific smooth-muscle actin and desmin, aid in distinguishing leiomyomas from other tumours." (PMID 39247034, 2024). "Sacral soft tissue biopsy and T11 spinal bone biopsy both demonstrated leiomyoma with immunostains positive for desmin, smooth muscle actin, and positive estrogen and progesterone receptors." (PMID 37457601, 2023). "stromal tumors and leiomyomas of the gastrointestinal tract were expressed to have negative S-100, with stromal tumors expressing positive CD34, CD117, and Dog-1, with Dog-1 being the most sensitive and SMA and Desmin being positive in leiomyoma." (PMID 35538511, 2022). "Microscopically, leiomyoma had the usual characteristics of a benign smooth muscle tumor with a clear boundary and stain for muscle markers such as desmin and smooth muscle actin." (PMID 35668195, 2022). "Immunohistochemical staining for desmin and actin, markers of smooth muscle differentiation, can be performed to detect these markers in leiomyomas." (PMID 27672473, 2016). "Positivity for S-100 protein and negativity for desmin and actin argue against leiomyoma and angiomyofibroblastoma." (PMID 23320233, 2012). "Leiomyomas similarly are devoid of S-100 protein, expressing smooth muscle actin and desmin instead." (PMID 22587439, 2012). "Leiomyoma is composed of spindle cells with cigar-shaped nuclei showing positivity for desmin and caldesmon." (PMID 23316399, 2012). "Immunohistochemical analysis to demonstrate smooth muscle differentiation, especially desmin, can usually be helpful in distinction between leiomyomas and fibromatous tumors." (PMID 19642987, 2009). "Histopathological examination revealed intersecting bundles of bland smooth muscle cells without atypia or necrosis, while immunohistochemistry demonstrated strong positivity for SMA, desmin, caldesmon, and estrogen receptors, consistent with pulmonary benign metastasizing leiomyoma." (PMID 41755927, 2026). "SMA and desmin positivity is typically indicative of leiomyoma." (PMID 40746605, 2025).
leiomyoma (continued). "Neurofibroma is rich in mucopolysaccharide, lacks a capsule, and has fewer axons; traumatic neuroma, while histologically similar to PEN and SCN, has inflammatory cells and scarring; and leiomyoma contains smooth muscle cells that stain positive for desmin and vimentin." (PMID 39463533, 2024). "Additionally, the immunohistochemical staining for desmin and h-caldesmon was implemented with a positive cytoplasmic reaction in leiomyoma cells." (PMID 36206804, 2022). "The immunohistochemical negativity for desmin excluded a leiomyoma." (PMID 31610454, 2019). "Leiomyomas are usually positive for desmin, SMA, CD117, CD34 and DOG-1 at low levels." (PMID 28492717, 2017). "The smooth muscle cells of the leiomyoma xenografts do express the smooth muscle marker Desmin." (PMID 26588841, 2015). "Spindle-shaped elements with elongated nuclei were appreciable; moreover, the cytoplasmatic immunohistochemical positivity for smooth muscle actin and desmin strongly supported the diagnosis of leiomyoma when also taking into account the constant negativity for CD34, CD117 and S100." (PMID 24959231, 2014). "Immunohistochemically leiomyomas of the tunica albuginea are positive for Desmin as we could show in the present case report, IMTs are negative." (PMID 23044187, 2012). "Hence, inclusion of desmin is necessary before considering leiomyoma." (PMID 38438897, 2024). "IMT typically expresses smooth muscle markers (desmin, SMA, caldesmon, transgelin) and stromal markers (CD10, IFITM1), which can lead to misdiagnosis as leiomyoma or endometrial stromal tumor." (PMID 41560086, 2026). "The postoperative routine pathological diagnosis was uterine spindle cell tumor (morphologically first considered leiomyoma with focal edema), and immunohistochemical detection showed SMA (+), Desmin (+), and Ki67 (+, 8%)." (PMID 41573634, 2025). "Immunohistochemical staining further confirmed a smooth muscle origin (desmin+, SMA+, and calponin+) with low proliferative activity (Ki-67 < 5%), consistent with a diagnosis of benign hydropic leiomyoma and excluding high-grade malignancy." (PMID 41199837, 2025). "GIST shows positive stains for CD 117, DOG-1, and CD 34, whereas leiomyoma expresses CD34, desmin, and SMA." (PMID 39027743, 2024). "Leiomyomas that originate in the gastrointestinal tract or omentum positively express SMA and Desmin and negatively express ER, PR, CD117, Dog-1, CD34, and S100, and the tumors are all composed of smooth muscle cells without endometrial components." (PMID 36086793, 2022). "Negative expression of other markers such as Dog-1, CD117, SMA, and desmin is useful for differentiating GISs from other mesenchymal tumors such as GIST and leiomyoma." (PMID 36582806, 2022). "Smooth muscle differentiation in leiomyomas is confirmed by positive staining for smooth muscle actin (SMA), h-Caldesmon, HHF35 and desmin, while immunohistochemical staining for CD34 and S100 protein is negative." (PMID 36611301, 2022). "It is important to differentiate angioleiomyoma from other types of spindle cell tumor, including leiomyoma (CD34- and S-100-), myopericytoma (desmin-, CD34-, and S100-), and myofibroma (desmin-, CD34-, and S-100-/+)." (PMID 30148476, 2018). "It is important to differentiate angioleiomyoma from other types of spindle cell tumor, including leiomyoma (CD34− and S-100−), myofibroma (desmin−, CD34− and S-100−/+) and myopericytoma (desmin−, CD34− and S100−)." (PMID 24959254, 2014). "Immunohistochemical staining differentiates leiomyomas from gastrointestinal stromal tumors (GISTs), with leiomyomas expressing desmin and smooth muscle actin (SMA) but lacking CD34 and KIT." (PMID 40177232, 2025). "Gastrointestinal stromal tumors were also excluded because the tumor cells were negative for CD117 and DOG-1, and leiomyoma was ruled out based on the negativity for desmin and SMA." (PMID 39889177, 2025).
leiomyoma (continued). "Immunohistochemical (IHC) staining was critical for differentiation from malignant gastrointestinal stromal tumors (GISTs), as leiomyomas were consistently positive for desmin and smooth muscle actin (SMA) but negative for CD34 and KIT." (PMID 40177232, 2025). "Conversely, leiomyoma accounts for desmin immunostaining and negative immunoreactivity for CD117 and CD34." (PMID 39994024, 2025). "The diagnosis is confirmed through immunohistochemical studies, where schwannomas typically stain positive for S-100 and SOX-10, unlike CD34, CD117, and desmin, which are markers for leiomyomas." (PMID 39554676, 2024). "Desmin is usually negative or very focally expressed in GIST, whereas leiomyomas show diffuse and strong positivity for desmin." (PMID 38609732, 2024). "A previous study reported that α-SMA-positive and desmin-negative cells as well as a large amount of collagen in leiomyoma tissue indicate the presence of myofibroblasts and their role in the ECM deposition." (PMID 39770574, 2024). "In one patient, histopathology was not entirely conclusive but favored a leiomyoma as the tumor was immunohistochemically positive for CD117 as well as for desmin." (PMID 37004654, 2023). "Smooth muscle cell markers, actin and desmin, will also be negative, differentiating it from leiomyomas." (PMID 32756198, 2020). "Smooth muscle cell markers (αSMA), actin and desmin, will also be negative, differentiating it from leiomyomas." (PMID 31102953, 2019). "Leiomyomas are also positive for desmin and smooth muscle actin, while GISTs are usually (but not always) negative." (PMID 23738186, 2013). "Human leiomyoma-derived fibroblasts (FB) were negative for desmin (center), suggestive of a non-muscle origin and positive for vimentin (upper left)." (PMID 20537183, 2010). "Leiomyomas are presented typically globally positive for desmin and smooth muscle actin, while they are negative for CD34 and CD117 (c-kit)." (PMID 20030817, 2009). "The leiomyoma was immunohistochemically positive for vimentin, α-smooth muscle actin, and desmin (1 case), but negative for cytokeratins, CD34, KIT, and PDGFRA." (PMID 27956961, 2009). "Only the focal positivity for desmin practically ruled out leiomyoma." (PMID 40735304, 2025). "Additionally, leiomyomas typically express markers of smooth muscle differentiation, such as desmin and smooth muscle actin, unlike most CFTs." (PMID 39512495, 2024). "Leiomyoma was ruled out based on negativity for desmin and smooth muscle actin." (PMID 38518040, 2024). "Leiomyoma can also be ruled out for lacking Desmin and strong Actin(SM) expression." (PMID 23227905, 2012). "Immunohistochemistry was positive for desmin and α-smooth muscle actin (αSMA), partially positive for CD34, and negative for S100, confirming leiomyoma." (PMID 41940047, 2026). "Histopathology showed interlacing fascicles of bland spindle cells with cigar-shaped nuclei, positive for SMA and desmin and negative for S-100 and CD34, confirming leiomyoma." (PMID 41300875, 2025). "Histopathological analysis revealed a schwannoma, with immunohistochemistry showing S-100 positivity and negative staining for C-KIT, CD34, actin, and desmin—key findings that helped differentiate it from other mesenchymal tumors, such as GIST or leiomyomas." (PMID 40507589, 2025). "Stains targeting smooth muscle-specific markers like SMA and desmin support their derivation from the smooth muscle, while CD34 and CD117 are negative in leiomyoma but positive in GIST." (PMID 39479071, 2024). "Immunohistochemical staining was positive for αSMA and desmin, negative for CD117 (KIT) and S100, and the patient was diagnosed with benign leiomyoma." (PMID 35620231, 2022). "Leiomyomas are positive for SMA, desmin, and muscle-specific actin and negative for CD117 (c-kit), CD34, and S100 protein." (PMID 31610453, 2019).
leiomyoma (continued). "Leiomyomas of deep somatic soft tissue are positive for smooth muscle actin (SMA), desmin, and caldesmon and expectedly are negative for a range of markers including cytokeratins, S100 protein, SOX-10, and CD34." (PMID 30271265, 2018). "Angioleiomyomas have an identical immunophenotype to leiomyomas of deep soft tissue, being positive for SMA and desmin and negative for S100 protein." (PMID 30271265, 2018). "In contrast to GIST, leiomyomas are uniformly negative for CD117 and CD34 and are positive for muscle markers including smooth muscle actin and desmin." (PMID 24991446, 2014). "Unlike GIST or leiomyoma, GCT is negative for KIT protein and Desmin." (PMID 34677732, 2022). "Leiomyomas usually stain positive for SMA and desmin but negative to CD117 and CD34." (PMID 34567524, 2021). "The primary diagnosis was cellular leiomyoma and now reviewed as GIST based on morphology and immunohistochemical staining results, which showed that the tumor cells were positive for CD117, but negative for CD34, a-SMA, desmin and S-100." (PMID 23902675, 2013). "However, IHC markers for smooth muscle differentiation (desmin, caldesmon, and SMA) stained negative could exclude benign leiomyoma." (PMID 36994196, 2023).